TLR3 (toll like receptor 3)
Diseases named in the same sentence as TLR3 in open-access papers (continued):
Sharing a sentence is not in itself a finding about the gene and the disease.
pulmonary sarcoidosis (2 papers, 2022 to 2023). Sarcoidosis affecting the lung parenchyma. "In particular, monomorphisms in TLR3 have been implicated in fibrotic pulmonary sarcoidosis, resulting in reduced TLR3 function in innate immune responses and reduced apoptosis of fibroblasts." (PMID 38202248, 2023). "In this study there was a significant association between this TLR3 polymorphism and persistent clinical disease in two cohorts of Irish and American Caucasians with pulmonary sarcoidosis." (PMID 36543347, 2022). "In a very small sub-study (n=3 patients), activation of TLR3 in primary lung fibroblasts from 412 F-homozygous pulmonary sarcoidosis patients resulted in reduced IFNB and TLR3 expression, and reduced apoptosis and dysregulated fibroproliferative responses compared with TLR3 wild-type patients." (PMID 36543347, 2022).
renal fibrosis (2 papers, 2022 to 2024). A final common manifestation of a wide variety of chronic kidney diseases characterized by glomerulosclerosis and tubulointerstitial fibrosis. "Inhibit the expression of Tgfbr1 by direct targeting to disrupt the TGF-β/Smad/TLR3 pathway, thus repressing renal fibrosis and the secretion of inflammatory factors in LN." (PMID 36187762, 2022). "Inhibiting pro-inflammatory cytokines and factors associated with renal fibrosis in human renal glomerular endothelial cells.Attenuating LN by targeting transforming growth factor beta receptor 1 (Tgfbr1), an enhancer of the TGF-β/Smad/TLR3 pathway." (PMID 39835138, 2024).
respiratory infections (2 papers, 2022 to 2023). "Simultaneous administration of two doses of vaccines also contributes to TLR3 expression which is observed only on monocytes, and, probably, the protective effect against other respiratory infections may be less pronounced." (PMID 37896869, 2023). "The intolerance of the inflammatory response induced by the intracellular TLRs might be related to the severe inflammation often seen in respiratory infections by RNA viruses or involved in viral-induced nasal allergic exacerbations through TLR3 activation." (PMID 35196817, 2022).
scleroderma (2 papers, 2011 to 2023). Scleroderma is a rare autoimmune connective tissue disorder characterized by abnormal hardening of the skin and, sometimes, other organs. "A study indicates that enriched genes including MPO (myeloperoxidase), RXFP1, CXCL11, CTNND2, BMPR2, TLR3, CCR2, and CAV1 are altered expressed in scleroderma." (PMID 38137330, 2023).
Sjögren syndrome (2 papers, 2012 to 2020). "TLR2, TLR3, and TLR4 were strongly expressed on the SGECs of patients with Sjögren syndrome, and TLR2 signaling induces the production of IL-23/IL-17 via IL-6 and signal transducer and activator of transcription (STAT) in the NF-κB pathway in Sjögren syndrome." (PMID 33224145, 2020).
skin cancer (2 papers, 2021 to 2024). "Hence, activating TLR3 during skin cancer may have a protective effect." (PMID 33510592, 2021). "Thus TLR3, TLR7/TLR8, and TLR9 activation are crucial therapeutic and adjuvant-based vaccine-oriented approaches to target skin cancers." (PMID 33510592, 2021). "However, we did not investigate the role of TLR3 in established skin cancers or how TLR3 may act in the fully transformed keratinocytes of BCCs and SCCs." (PMID 39348939, 2024).
status epilepticus (2 papers, 2023 to 2024). Status epilepticus is defined as a continuous seizure lasting more than 30 min, or two or more seizures without full recovery of consciousness between any of them. "Additionally, TLR3-deficient mice demonstrated enhanced survival rates post-status epilepticus." (PMID 38792602, 2024). "We hypothesized that pharmacological inhibition of TLR3 would reduce epileptogenesis following status epilepticus." (PMID 37694107, 2023). "Furthermore, TLR3 deficiency has been shown to reduce spontaneous recurrent seizures, microglial activation, and levels of proinflammatory cytokines TNF-α and IFN-β following status epilepticus." (PMID 38792602, 2024).
systemic anaphylaxis (2 papers, 2018 to 2020). "Nevertheless, these findings add to the previous data demonstrating that IL-33 acts via ST2 to increase mast cell surface IgE, and to trigger histamine release and systemic anaphylaxis in naïve mice and that poly I:C activates mast cells via TLR3, which may result in the recruitment of CD8+ cells." (PMID 30337928, 2018).
ulcerative colitis (2 papers, 2018 to 2025). An inflammatory bowel disease involving the mucosal surface of the large intestine and rectum. "It was reported that there were little differences in TLR3 expression at different sites or between non-inflamed and inflamed mucosae in tissues from ulcerative colitis patients." (PMID 29515574, 2018).
uterine corpus endometrial carcinoma (2 papers, 2022 to 2025). A endometrial carcinoma (disease) that involves the body of uterus. "Through the results, it was observed that the two datasets of cancer types- CESC (cervical adenocarcinoma) and UCEC (Uterine corpus endometrial carcinoma) arise due to the overexpression of the TLR3 gene." (PMID 40847033, 2025). "In the SNV percentage analysis, we found that the number of samples in which the necroptosis-related regulators had deleterious mutations was greater in uterine corpus endometrial carcinoma (UCEC) and SKCM, especially TLR3, with the highest mutation frequency among all cancer types." (PMID 35748782, 2022). "Gene expression profiling using GEPIA2 revealed that TLR3 expression is upregulated in both cervical squamous cell carcinoma (CESC) and uterine corpus endometrial carcinoma (UCEC)." (PMID 40847033, 2025).
vasculitis (2 papers, 2014 to 2024). "Various TLRs, including TLR3 and TLR7 had been found upregulated in IgA vasculitis; this suggests their possible involvement in the pathogenesis of the vasculitis." (PMID 37500944, 2024).
viral respiratory tract infection (2 papers, 2020 to 2022). A respiratory tract infection caused by a virus. "Although we focused on the TLR3-mediated immune response, real viral respiratory tract infection can induce various responses that could also contribute to the status of the olfactory system." (PMID 35012562, 2022).
Acute bronchitis (1 paper, 2026). Inflammation of the large airways of the lung with rapid onset and short course usually associated with cough, mucus production, shortness of breath, wheezing, and chest tightness. "Key findings highlighted Pelargonium sidoides as the most extensively studied herb, acute bronchitis as the predominant condition, respiratory syncytial virus (RSV) as the main pathogen, and the toll-like receptor 3 (TLR3) signaling pathway as a pivotal therapeutic target." (PMID 41675215, 2026).
acute kidney injury (1 paper, 2014). Sudden and sustained deterioration of the kidney function characterized by decreased glomerular filtration rate, increased serum creatinine or oliguria. "Thus, we conclude that TLR-3 seems to participate in the pathogenesis of early acute kidney injury." (PMID 24736450, 2014).
acute lymphoblastic leukemia (1 paper, 2014). Leukemia with an acute onset, characterized by the presence of lymphoblasts in the bone marrow and the peripheral blood. "In acute lymphoblastic leukemia (ALL) cell lines, TLR1, TLR2, TLR3, TLR4, TLR6 and TLR7 are expressed albeit at variable levels." (PMID 25112836, 2014).
acute myeloid leukemia (1 paper, 2023). Acute myeloid leukemia (AML) is a group of neoplasms arising from precursor cells committed to the myeloid cell-line differentiation. "Here, we report that malignant blasts from patients with acute myeloid leukemia (AML) release type I IFN via a Toll-like receptor 3 (TLR3)-dependent mechanism that is not driven by treatment." (PMID 36964168, 2023).
adenocarcinomas of the breast (1 paper, 2008). "Since both poly I:C and poly(A:U) have been used with moderate success as immune adjuvant therapy in clinical trials for different types of cancer, including adenocarcinomas of the breast, our findings may open a new range of the applications for TLR3 agonists as an adjuvant of cancer chemotherapy." (PMID 18199340, 2008).
alcohol abuse (1 paper, 2022). The use of alcoholic beverages to excess, either on individual occasions ("binge drinking") or as a regular practice. "A recent study on alcohol-induced liver disease (ALD) and intestinal damage, based on a chronic-binge alcohol abuse model, explored the therapeutic mechanisms of pre-activated (with toll-like receptor 3; TLR3) bone marrow-derived mesenchymal stem cells (P-BMMSCs)." (PMID 36405684, 2022).
alcoholic hepatitis (1 paper, 2022). Acute hepatitis resulting from ingestion of alcohol. "However, TLR3/4 also mediates the NF-κB-CXCR4/7 pathway in the formation of Mallory–Denk bodies in human alcoholic hepatitis and NASH." (PMID 36397950, 2022). "Mallory–Denk bodies formed in human alcoholic hepatitis and NASH can mediate TLR3/4 signaling through the NF-κB-CXCR4/7 pathway." (PMID 36397950, 2022).
allergic contact dermatitis (1 paper, 2023). An inflammatory skin condition caused by an immune response to direct contact between the skin and an allergen. "First, the potential anti-inflammatory effects of DMG-Na were assessed on toll-like receptor (TLR)-3 activation-induced cultured human HaCaT keratinocytes, a well-established in vitro model of microbial and allergic contact dermatitis." (PMID 37511024, 2023).
anaemia (1 paper, 2018). "The TLR3 gene rs3775296-T risk allele was found to be associated with anaemia and photosensitivity in Taiwanese SLE patients indicating that TLR3 involved the development of different SLE phenotypes, and in antiviral responses that trigger expression of pro-inflammatory genes." (PMID 29650017, 2018).
Atrophy (1 paper, 2015). Any weakening or degeneration, especially through lack of use. "Moreover, ILCs express TLR3 and are functionally able to respond to poly I:C with increased synthesis of TNF-α thus contributing to small intestinal atrophy." (PMID 25950701, 2015).
autoimmune uveitis (1 paper, 2013). An autoimmune form of uveitis (disease). "Our previous studies showed that signaling of TLR2, TLR3, TLR4, and TLR9 is highly redundant in the adjuvant effect needed to induce experimental autoimmune uveitis (EAU)." (PMID 23207548, 2013).
B-cell lymphoma (1 paper, 2018). "The EGFR/TLR3 axis activated by TAR RNA is specific for carcinoma cells that express EGFR, since B-cell lymphoma cells that lack EGFR do not respond to the HIV-positive exosomes for proliferation." (PMID 30389917, 2018).
bacterial meningitis (1 paper, 2017). Inflammation of the membranes surrounding the brain and spinal cord due to a bacterial infection. "We investigated whether bacterial meningitis (BM) in children was associated with gene polymorphisms in TLR2 (rs3804099), TLR3 (rs3775291 and rs3775290) and TLR9 (rs352139 and rs352140)." (PMID 28202935, 2017).
bladder tumors (1 paper, 2021). "Therefore, the effect of BCG treatment on bladder tumors is independent of TLR3 and the cGAS-STING pathway." (PMID 34341449, 2021).
calcific aortic valve disease (1 paper, 2018). "Moreover, recent in vivo data presented at European Society of Cardiology Congress 2017 have associated TLR3 to the onset of calcific aortic valve disease by using TLR3- and ApoE-deficient mice models." (PMID 29593562, 2018).
celiac disease (1 paper, 2025). An autoimmune genetic disorder with an unknown pattern of inheritance that primarily affects the digestive tract. "Celiac disease is closely regulated by TLR3 signaling, as downstream induction of interferons and cytokines is responsible for the pathogenesis in mice." (PMID 39988665, 2025). "The histological changes following TLR3 agonism can be attributable to rapid IFN-β secretion, which may favor a characteristic Th1 profile in celiac disease." (PMID 39988665, 2025).
cervical tumor (1 paper, 2014). "The incubation of macrophages with supernatant from cervical tumor cells induced profound effects on TLR expression, because TLR-3, -7, and -9 are upregulated in M1 macrophages, mainly in the presence of supernatant from cells infected with HPV, such as HeLa and SiHa." (PMID 25309919, 2014).
Chagas disease (1 paper, 2018). A parasitic infection caused by Trypanosoma cruzi. "Patients with different clinical manifestations of Chagas disease showed similar expression of TLR1, TLR3, TLR4, TLR5, TLR6, TLR7 and TLR9 mRNA." (PMID 30044791, 2018). "On the other hand, patients with different clinical manifestations of Chagas disease showed similar mRNA expression levels of TLR1, TLR3, TLR4, TLR5, TLR6, TLR7 and TLR9." (PMID 30044791, 2018).
childhood cancers (1 paper, 2023). "We thus assessed the allelic status of TLR3 in several childhood cancer cell lines." (PMID 37414800, 2023).
cholangiocarcinoma (1 paper, 2020). A carcinoma that arises from the intrahepatic biliary tree (intrahepatic cholangiocarcinoma) or from the junction, or adjacent to the junction, of the right and left hepatic ducts (hilar cholangiocarcinoma). "Therefore, we examined the status of TLR3 in cholangiocarcinoma (CCA) cases to better understand TLR3 signaling and explore the potential therapeutic target in CCA." (PMID 33036630, 2020).
cholangitis (1 paper, 2015). An acute or chronic inflammatory process affecting the biliary tract. "In a previous study, administration of polyI:C, a viral RNA mimetic and Toll-like receptor 3 agonist, to activate NK cells in 2-OA-BSA immunized mice, induces profound exacerbation of cholangitis." (PMID 25807531, 2015).
chronic lymphocytic leukemia (1 paper, 2023). "In this study, we aim to unravel the intricate involvement of TLR2, TLR4, TLR3, TLR7, TLR8, and TLR9 in the immunopathogenesis of common variable immunodeficiency—CVID (as PID)—and chronic lymphocytic leukemia—CLL (as SID)." (PMID 37626865, 2023).
chronic salpingitis (1 paper, 2018). Chronic inflammation of the fallopian tube. "The exact mechanism on how TLR3 contributes to hydrosalpinx in mice remains enigmatic, but this lesion may have developed as a result of the chronic salpingitis from earlier time points of C. muridarum infection." (PMID 29624589, 2018).
Cm (1 paper, 2018). "Our previous data also showed IL-6 and CCL5 synthesis was diminished during early stages of Cm infection in the genital tract of TLR3-/- mice from a 129S1 genetic background." (PMID 29624589, 2018). "Because TLR3 modulates the release inflammatory mediators involved in host defense during Cm infection, we hypothesized that TLR3 plays a protective role against Cm-induced genital tract pathology in congenic C57BL/6N mice." (PMID 29624589, 2018).
CNS demyelination (1 paper, 2016). A loss of myelin from nerve fibers in the central nervous system. "Poly-IC a known TLR3 agonist and IL-33, a cytokine which is induced by poly-IC are known to influence recovery and promote repair in experimental models of CNS demyelination." (PMID 27022724, 2016).
cocaine addiction (1 paper, 2018). "In the present study, we aimed to define the role of TLR3 in cocaine addiction and its associated inflammatory immune signaling." (PMID 29571298, 2018). "In the present study, we investigated the potential role of TLR3 signaling in cocaine addiction." (PMID 29571298, 2018). "The present study was designed to investigate the potential role of TLR3 in cocaine addiction." (PMID 29571298, 2018). "We propose that TLR3 blockade could be a novel approach to treat cocaine addiction." (PMID 29571298, 2018). "Our findings show that TLR3 is a novel contributor to cocaine-induced reward behaviors and TLR3/dsRNA complex inhibitor might serve as potential therapeutic targets for the treatment of cocaine addiction." (PMID 29571298, 2018).
cocaine use disorder (1 paper, 2021). A substance-related disorder that involves the recurring use of cocaine despite negative consequences. "Further studies are needed to assess whether Ex4 can exert neuroprotective effects for treating cocaine use disorder by blocking TLR3 and TLR2 signaling or through other factors." (PMID 34349653, 2021).
colorectal polyp (1 paper, 2020). "The noteworthy point was that the RQs of TLR2, TLR3, TLR4, and TLR5 were significantly different among histologically different colorectal polyp types compared to samples from normal participants (p-value < 0.001)." (PMID 33255933, 2020). "In fact, TLR3 and TLR5 expression levels were higher in normal individuals, compared to different types of progressive colorectal polyps." (PMID 33255933, 2020). "The aim of our study was to evaluate the expression levels of TLR2, TLR3, TLR4, and TLR5 in intestinal biopsy specimens of patients with different histological colorectal polyp types including HP, SSA, tubular adenoma (TA), and villous/tubulovillous (VP/TVP) cases compared to normal controls." (PMID 33255933, 2020).
cutaneous candidiasis (1 paper, 2012). Candidiasis of the skin manifested as eczema-like lesions of the interdigital spaces, perleche, or chronic paronychia. "By contrast, TLR3 L412F SNP is associated with increased prevalence of cutaneous candidiasis and impaired TLR3 signaling." (PMID 23189270, 2012).
cutaneous squamous cell carcinoma (1 paper, 2024). "Using immunohistochemistry, we stained 21 established cutaneous squamous cell carcinomas (cSCCs) and BCCs for TLR3 protein to confirm its expression and localization within tumors." (PMID 39348939, 2024).
demyelination (1 paper, 2020). "To more closely mimic demyelination conditions, we next examined whether TLR3 agonist Poly(I:C) also induces fibronectin aggregation in ex vivo organotypic cerebellar slice cultures." (PMID 31953424, 2020).
drug dependence (1 paper, 2018). "Taken together, the results of this study provide evidence that TLR3 plays a critical role in cocaine-induced behavioral effects and further insight into the link between innate immunity and drug dependence." (PMID 29571298, 2018).
Duchenne muscular dystrophy (1 paper, 2011). Duchenne muscular dystrophy (DMD) is a neuromuscular disease characterized by rapidly progressive muscle weakness and wasting due to degeneration of skeletal, smooth and cardiac muscle. "TLR3 and TLR7 are elevated in inflammatory myopathies as is TLR7 in muscles of Duchenne muscular dystrophy patients." (PMID 21850221, 2011).
Dysmenorrhea (1 paper, 2017). Pain during menstruation that interferes with daily activities. "After statistical analysis confirmed that: The gene expression of TLRS (TLRS = TLR1 + TLR2 + TLR3 + TLR4 + TLR5 + TLR6 + TLR7 + TLR8 + TLR9) in severe and moderate dysmenorrhea group was significantly higher than that in minimal dysmenorrhea group in EU and EC (P < 0.05 or P < 0.01)." (PMID 28779087, 2017).
endometrial adenocarcinoma (1 paper, 2008). "TLR3 and TLR4 mRNA expression varied significantly between control, hyperplasia and endometrial adenocarcinoma samples (Kruskal-Wallis test, P < 0.01)." (PMID 18775079, 2008). "TLR3 and TLR4 expression was investigated during the menstrual cycle and in postmenopausal endometrium considering peritoneal endometriosis, hyperplasia, and endometrial adenocarcinoma specimens (grade 1 to 3)." (PMID 18775079, 2008).
endometrial carcinoma (1 paper, 2008). A malignant tumor arising from the epithelium that lines the cavity of the uterine body. "TLR3 and TLR4 proteins in hyperplasia and endometrial carcinoma were mostly localized to the luminal and glandular epithelium." (PMID 18775079, 2008).
enteropathy (1 paper, 2014). "Systemic administration of polyinosinic:polycytidylic acid (poly I:C), mimics virally-induced activation of TLR3 signalling causing acute small intestine damage, but whether and how mucosal administration of poly I:C causes enteropathy is less clear." (PMID 24915573, 2014).
eosinophilia (1 paper, 2016). "For instance, TLR3 signaling regulates eosinophilia-associated cytokine production in CRSwNP via IL-10 production." (PMID 27584662, 2016).